MPO (myeloperoxidase)
Diseases named in the same sentence as MPO in open-access papers (continued):
Sharing a sentence is not in itself a finding about the gene and the disease.
abdominal aortic aneurysm (7 papers, 2021 to 2026). Enlargement and ballooning of the vessel that supplies arterial blood to the abdomen, pelvis and legs. "Myeloperoxidase is an enzyme linked to the generation of neutrophil-derived reactive oxygen species and is suggested to be a key contributor to the inflammatory aspects of atherogenesis and the formation of abdominal aortic aneurysms." (PMID 39407935, 2024). "Inflammation also plays a key role in abdominal aortic aneurysms, where myeloperoxidase, tissue-type plasminogen activators, and cystatin-B levels were significantly associated with AbAA growth, even after adjusting for baseline AbAA diameter." (PMID 34441429, 2021). "Abdominal aortic aneurysm (AAA) and peripheral artery disease (PAD) share pathophysiological mechanisms including the activation of the fibrinolytic and innate immune system, which explains the analysis of D-dimer and myeloperoxidase (MPO) in both conditions." (PMID 38137627, 2023). "The present report evaluates the performance of the MPO/D-dimer score in the context of AAA vs. PAD, i.e., addresses the question of whether the score is suited to distinguishing abdominal aortic aneurysm from this athero-occlusive disease." (PMID 38137627, 2023). "Despite the fact that we have recently reported the circulating NET parameter citH3 to be significantly elevated in the chronic inflammatory setting of abdominal aortic aneurysms, plasma MPO-DNA complex levels determined by ELISA did not correlate with citH3." (PMID 33886636, 2021).
amyotrophic lateral sclerosis (7 papers, 2017 to 2025). Amyotrophic lateral sclerosis (ALS) is a neurodegenerative disease characterized by progressive muscular paralysis reflecting degeneration of motor neurons in the primary motor cortex, corticospinal tracts, brainstem and spinal cord. "This randomized clinical trial investigated the effect of verdiperstat, a myeloperoxidase inhibitor, in amyotrophic lateral sclerosis." (PMID 40067754, 2025). "What is the effect of verdiperstat, a myeloperoxidase inhibitor, in amyotrophic lateral sclerosis?" (PMID 40067754, 2025). "Myeloperoxidase inhibitors may have a clinical benefit in amyotrophic lateral sclerosis (ALS) by slowing neurodegeneration via reduced neuroinflammation and oxidative stress." (PMID 40067754, 2025).
autoimmune hepatitis (7 papers, 2014 to 2025). Hepatitis caused by autoantibodies. "Due to their pro-inflammatory action, more and more attention is paid to the role of LDGs, including those expressing the enzyme myeloperoxidase (MPO), in the development of autoimmune hepatitis (AIH)." (PMID 35456267, 2022). "There was no agreement between ANCA patterns and antigenic specificities in IBD and autoimmune liver diseases, which reinforces the need for proteinase-3 and myeloperoxidase antibody testing." (PMID 33567045, 2021).
bacterial meningitis (7 papers, 2019 to 2025). Inflammation of the membranes surrounding the brain and spinal cord due to a bacterial infection. "The detection of neutrophil extracellular traps MPO and associated inflammatory protein levels in cerebrospinal fluid samples holds promise in prognosticating bacterial meningitis, thereby assuming paramount significance in the prognostic evaluation of patients afflicted with this condition." (PMID 38802752, 2024). "We conducted a correlation analysis between MPO values and clinically significant test indicators to demonstrate that MPO is significantly correlated with inflammatory proteins in bacterial meningitis." (PMID 38802752, 2024). "Because neutrophils are crucial mediators of host defenses during acute bacterial meningitis, neutrophil counts and myeloperoxidase (MPO) activity (an indirect indicator of neutrophil recruitment) in the brain after infection were assessed." (PMID 33318141, 2021). "The immunological response in bacterial meningitis (BM) causes the formation of reactive oxygen and nitrogen species (ROS, RNS) and activates myeloperoxidase (MPO), an inflammatory enzyme." (PMID 31581487, 2019). "Matrix metalloproteinases (MMPs) and myeloperoxidase (MPO) contribute to the inflammatory cascade in the cerebrospinal fluid (CSF) during bacterial meningitis." (PMID 31780869, 2019). "We determined levels of MPO, MMP-8, MMP-9, and tissue inhibitor of metalloproteinase- (TIMP-) 1 in the CSF of children with bacterial meningitis and investigated how these inflammatory mediators relate to each other and to the disease outcomes." (PMID 31780869, 2019).
gastric cancer (7 papers, 2016 to 2025). A primary or metastatic malignant neoplasm involving the stomach. "This selective downregulation pattern in gastric cancer parallels our findings in healthy cohorts, where elevated MPO was associated with reduced PGR (primarily driven by PGI suppression)." (PMID 40547041, 2025). "Epidemiological studies demonstrate that MPO polymorphism influences the risk of gastric cancer." (PMID 37124627, 2023). "The results imply that MPO may be associated with gastric cancer progression." (PMID 40547041, 2025). "To further investigate the cellular sources of MPO and pepsinogens in gastric cancer, we performed single-cell RNA-seq analysis of gastric cancer (GSE210347) using scCancerExplorer." (PMID 40547041, 2025). "Myeloperoxidase (MPO) is a key enzyme involved in immune responses and oxidative stress, yet its roles in gastric physiology and gastric cancer remain incompletely understood." (PMID 40547041, 2025). "In this study, our goal was to investigate the relationship between MPO and pepsinogen levels, immune modulation, and prognosis in gastric cancer patients, to better understand MPO’s role in gastric health and cancer." (PMID 40547041, 2025). "This study explored the role of MPO in gastric cancer by analyzing data from 375 gastric adenocarcinoma patients in the TCGA cohort." (PMID 40547041, 2025). "Given that serum PGR is a biomarker for gastric cancer, to explore the potential link between MPO and gastric cancer, we conducted subgroup and interaction analyses while validating the relationship between MPO and PGR." (PMID 40547041, 2025). "It is noteworthy that during gastric cancer progression, there is prolonged oxidative stress, accompanied by increased MPO levels." (PMID 40547041, 2025). "In gastric cancer, patients or animal models exhibit features of increased MPO-positive cell infiltration and elevated expression levels, suggesting that MPO plays a critical role in gastric cancer." (PMID 40547041, 2025). "MPO, a DNA repair-relevant biomarker, is induced by alcohol with prognostic implication in gastric cancer." (PMID 37124627, 2023). "We presume that this is because the previous study evaluated early gastric cancer, and they measured TANs primarily by HE staining with the aid of myeloperoxidase IHC." (PMID 35327509, 2022). "We also analyzed the expression of MPO and E-cadherin protein levels in gastric cancer and cancer adjacent tissue control lysates by western blot." (PMID 27412620, 2016). "This study highlights the distinct roles of MPO in gastric mucosal injury and gastric cancer." (PMID 40547041, 2025). "Finally, this study is the first to comprehensively analyze the role of MPO in gastric health and gastric cancer, offering a potential new biomarker for the early diagnosis and prevention of gastric adenocarcinoma." (PMID 40547041, 2025). "However, the function and potential clinical significance of MPO in gastric cancer remain insufficiently explored." (PMID 40547041, 2025). "e.g., our preliminary data in stomach cancer-affected wall showed that MPO-positive cells were more numerous in the stomach wall close to cancer infiltration, whereas the number of CD38-positive cells was similar in the tissue localized close and distally from cancer." (PMID 30373200, 2018). "Although MPO is correlated with the malignancy and survival prognosis of gastric cancer, further functional experiments are needed to determine whether MPO holds potential as a therapeutic target for gastric cancer." (PMID 40547041, 2025). "This study experimentally verified the levels of DNA repair-relevant genes, with higher levels of PAPPA2, MPO, MAGEA11, DEPP1, CPZ, and COLEC12 and lower level of CYTL1 in gastric cancer cells versus controls." (PMID 37124627, 2023). "Higher levels of PAPPA2, MPO, MAGEA11, DEPP1, CPZ, and COLEC12 and lower level of CYTL1 were proven in gastric cancer cells versus controls." (PMID 37124627, 2023).
gastric cancer (continued). "In contrast to gastric mucosa epithelial cell line GES-1, transcriptional levels of PAPPA2, MPO, MAGEA11, DEPP1, CPZ, and COLEC12 were higher in gastric cancer cell lines HGC-27, MKN-28 and AGS, with lower transcriptional level of CYTL1." (PMID 37124627, 2023). "We acknowledge that the inverse but non-linear MPO-PGR relationship observed in healthy cohorts represents a key limitation, as extrapolating these findings to disease states, such as gastric cancer, requires caution." (PMID 40547041, 2025).
intracerebral hemorrhage (7 papers, 2019 to 2025). A cerebrovascular disorder characterized by bleeding into one or both cerebral hemispheres including the basal ganglia and the cerebral cortex. "We extend previous results from a 2017 study which found that an MPO-increasing polygenic score based on a 2013 MPO GWAS meta-analysis was correlated with elevated risk of both primary and recurrent intracerebral haemorrhage." (PMID 35504531, 2022). "These suggest that intracerebral hemorrhage significantly increases inflammatory cytokine levels and myeloperoxidase activity, which, in turn, promotes an inflammatory response in the intestine, leading to gastrointestinal disorders associated with intestinal motility and barrier dysfunction." (PMID 36895909, 2023).
leukopenia (7 papers, 2012 to 2025). "As drugs such as cyclophosphamide that cause leukopenia prevented calcification, we next investigated whether administration of an MPO inhibitor to blunt neutrophil-mediated response could also attenuate ectopic cutaneous calcification." (PMID 41031886, 2025).
myositis (7 papers, 2017 to 2025). "This case discusses a patient presenting primarily with features of myositis (including muscle weakness) in the setting of MPO-positive AAV." (PMID 39077221, 2024). "In the present study, we also investigated tumor markers, onconeural antibodies and coexistent anti-thyroid autoantibodies, anti-nuclear/myositis/ganglioside antibody profiles, and anti-MPO/PR3/AchR/AQP4 antibodies." (PMID 29180979, 2017). "Ultimately, the patient was diagnosed with myositis secondary to MPO-positive AAV." (PMID 39077221, 2024). "Therefore, SLE patients with high serum levels of the MPO-DNA complex were characterized by a higher frequency of myositis and pleurisy, higher serum level of CRP, and lower titers of anti-dsDNA antibodies." (PMID 36319843, 2022). "Notably, the frequencies of myositis and pleurisy were significantly higher in SLE patients who had high serum MPO-DNA than in those with low levels while the frequency of other clinical manifestations were not dependent on MPO-DNA complex levels." (PMID 36319843, 2022).
overlap syndrome (7 papers, 2016 to 2025). "Regarding nine ANCA-positive patients diagnosed with overlap syndrome consisting of PM/DM and MPA, all nine patients had MPO-ANCA (or P-ANCA) positivity." (PMID 37959218, 2023). "In terms of ILD, even though it may not be possible to discriminate whether ILD is a clinical feature of MPA or of PM/DM, why should we focus on the diagnosis of overlap syndrome consisting of PM/DM and MPA in nine patients having MPO-ANCA (or P-ANCA) and ILD?" (PMID 37959218, 2023). "Therefore, this patient achieved a total score of 6 because of MPO-ANCA (or P-ANC A) positivity and was diagnosed with overlap syndrome consisting of PM/DM and MPA." (PMID 37959218, 2023). "Patients with SLE/AAV overlap syndrome are mostly female, present with a severe clinical presentation (rapidly progressive GN and frequent pulmonary involvement), and have both ANA and anti-MPO antibodies." (PMID 27258503, 2016).
prostate carcinoma (7 papers, 2020 to 2026). A carcinoma that arises from epithelial cells of the prostate gland. "Elevated levels of MPO are associated with a higher tumor grade and stage in prostate cancer, suggesting its role as a prognostic biomarker." (PMID 39336493, 2024). "Research has demonstrated that MPO is significantly linked to the risk of prostate cancer (PCa) through single nucleotide polymorphisms." (PMID 39834542, 2024). "While MPO’s exact role in prostate cancer progression remains unclear, it is likely linked to its pro-oxidative and inflammatory effects rather than direct genotoxicity." (PMID 39336493, 2024). "Those with the MPO GG variation were expected to have the greater ability to upregulate oxidative stress while those with GA/AA variants were compromised, i.e., with a 2-fold increase in aggressive prostate cancer risk among men with low n-3 LC-PUFA." (PMID 32498320, 2020). "However, recent studies have highlighted a potentially paradoxical role of MPO in the progression of several cancers, including prostate cancer." (PMID 39336493, 2024).
renal dysfunction (7 papers, 2014 to 2025). "A clinical study further corroborates these findings, showing that AKI patients exhibit elevated serum levels of cf-DNA and MPO-DNA, which correlate with renal dysfunction (elevated Scr and BUN) and pro-inflammatory cytokines IL-1β and TNF-α release." (PMID 41244813, 2025). "MPO-DNA was found in lower concentrations in patients that received corticosteroids before established renal dysfunction (p = 0.03) and was found in higher concentrations in patients with AKI stage 3 (p = 0.03)." (PMID 39340756, 2024). "A 79-year-old woman developed serious renal dysfunction and pulmonary alveolar hemorrhaging due to MPO–ANCA and anti-GBM antibody double-positive vasculitis." (PMID 31612361, 2020).
Salmonella Infections (7 papers, 2014 to 2023). Infections with bacteria of the genus SALMONELLA. "Our results suggest that hypoxia induces more severe liver and spleen infections in MPO-deficient mice during Salmonella infection." (PMID 38037141, 2023). "To determine whether hypoxia enhances bacterial migration and whether the increased susceptibility to Salmonella infection in the MPO-deficient mice is related to increased bacterial replication, we investigated bacterial translocation to the spleen and liver at 72 h after infection." (PMID 38037141, 2023). "In this study, we determined the functional role of hypoxia and MPO in controlling systemic and intestinal mucosal Salmonella infections and the interaction between the two." (PMID 38037141, 2023). "To further study the effects of hypoxia and MPO on the innate immunity against Salmonella infection, we analyzed the spleen tissue’s frequency of neutrophils and macrophages." (PMID 38037141, 2023). "MPO mediates the innate immune response and regulates the mucosal and systemic inflammatory responses to Salmonella infection during hypoxia." (PMID 38037141, 2023). "Salmonella infection promoted chemokine expression in colon tissue, and the upregulated chemokines were significantly different in both WT-infected and MPO−/−-infected mice." (PMID 38037141, 2023). "In the present study, the increase in serum MPO activities of the SAL group suggested that Salmonella infection could activate monocytes and neutrophils in blood and promote intestinal inflammations." (PMID 29396554, 2018). "Heterophils can be found in the lamina propria of the ceca within hours after Salmonella infection and are reliant more on degranulation to kill bacteria than an oxidative burst due to the lack of myeloperoxidase." (PMID 26664916, 2014). "Another study showed that probiotic Lactobacillus efficiently reduced Salmonella infection and gut inflammation by increasing the levels of propionic acid and mucin-2, as well as changing the level of tumor necrosis factor-alpha (TNF-a), interleukin-10 (IL-10) and myeloperoxidase (MPO) in mice." (PMID 32150574, 2020).
allergic rhinitis (6 papers, 2008 to 2025). Inflammation of the nasal mucous membranes caused by an IgE-mediated response to external allergens. "The nasal lavage fluid levels of MPO post-TNF-α challenge were increased in patients with allergic rhinitis." (PMID 27046957, 2016). "MPO release from neutrophils spontaneously and after C3b-stimulation (at 0 and 20 min) in allergic rhinitis and allergic asthma during pollen season and after nasal and bronchial challenge." (PMID 21255397, 2011). "C3b-induced degranulation resulted in increased release of ECP and MPO from primed blood eosinophils and neutrophils in both allergic rhinitis and allergic asthma during pollen season and after both nasal and bronchial challenge (p-values 0.008 to 0.043)." (PMID 21255397, 2011). "Nasal lavage fluid levels of MPO recorded 24 hours post TNFα challenge were increased in healthy subjects (p = 0.0081) and in patients with allergic rhinitis (p = 0.0081) (c.f." (PMID 18234086, 2008). "The finding is in agreement with our previous observation in allergic rhinitis, although that particular increase in MPO only reached borderline statistical significance." (PMID 18234086, 2008). "Nasal lavage fluid levels of MPO were increased 24 hours post TNFα administration in healthy subjects and in patients with allergic rhinitis (this study)." (PMID 18234086, 2008). "Nasal lavage fluid levels of MPO recorded 24 hrs post TNFα challenge were increased in healthy subjects (p = 0.0081) and in patients with allergic rhinitis (p = 0.0081) (c.f." (PMID 18234086, 2008). "A significant increase of ECP and MPO could be recorded in both patients with allergic rhinitis and allergic asthma." (PMID 21255397, 2011). "There were no significant increases in degranulation of ECP, EPO or MPO in patients with allergic rhinitis, allergic asthma or in the control group." (PMID 21255397, 2011). "The spontaneous release of MPO significantly increased in the asthmatic group, but not in patients with allergic rhinitis." (PMID 21255397, 2011). "There was a similar tendency for stimulated MPO release in allergic rhinitis but this was not significant." (PMID 21255397, 2011).
bacteremia (6 papers, 2015 to 2024). "To examine whether these mechanisms are relevant during bacterial sepsis, we infected MPO and T cell-deficient animals systemically with Staphylococcus aureus." (PMID 35945238, 2022). "Given our observations of increased intestinal permeability and bacteremia in baso IL-4/IL-13 (−) mice, we assayed plasma MPO and NE, antimicrobial effectors frequently used as markers for neutrophil activation." (PMID 38780542, 2024). "On day 7, animal survival, diarrhea and bacteremia were assessed, and following euthanasia, samples of the ileum were obtained for morphometric analysis, myeloperoxidase (MPO) assay and measurement of pro-inflammatory markers." (PMID 26440613, 2015).
Behçet Disease (6 papers, 2018 to 2025). "At immunohistochemistry and immunofluorescence, we can find a positivity for MPO (myeloperoxidase), which is a lysosomal neutrophilic enzyme whose implication in tissue damage from Behçet Disease has been demonstrated." (PMID 37629654, 2023).